LEF1 (lymphoid enhancer binding factor 1)
Description:
Transcription factor that binds DNA in a sequence-specific manner. Participates in the Wnt signaling pathway (By similarity). Activates transcription of target genes in the presence of CTNNB1 and EP300 (By similarity). PIAG antagonizes both Wnt-dependent and Wnt-independent activation by LEF1 (By similarity). TLE1, TLE2, TLE3 and TLE4 repress transactivation mediated by LEF1 and CTNNB1. Regulates T-cell receptor alpha enhancer function. Required for IL17A expressing gamma-delta T-cell maturation and development, via binding to regulator loci of BLK to modulate expression (By similarity). Acts as a positive regulator of odontoblast differentiation during mesenchymal tooth germ formation, expression is repressed during the bell stage by MSX1-mediated inhibition of CTNNB1 signaling (By similarity). May play a role in hair cell differentiation and follicle morphogenesis (By similarity). [Isoform 1]: Transcriptionally activates MYC and CCND1 expression and enhances proliferation of pancreatic tumor cells. [Isoform 3]: Lacks the CTNNB1 interaction domain and may therefore be an antagonist for Wnt signaling. [Isoform 5]: Transcriptionally activates the fibronectin promoter, binds to and represses transcription from the E-cadherin promoter in a CTNNB1-independent manner, and is involved in reducing cellular aggregation and increasing cell migration of pancreatic cancer cells.
Synonyms: LEF-1; TCF1ALPHA; TCF10; TCF7L3; ECTD1; ECTD17
Tractability: PROTAC: UniProt records ubiquitination sites on it; ubiquitination databases record sites on it; a small molecule that binds it is known.
Target class: Transcription factor
Gene: Protein-coding gene on chromosome 4 (108,047,545 to 108,168,956, reverse strand). Ensembl gene ENSG00000138795.
Subcellular location: Nucleus
Subcellular location (Human Protein Atlas): Nucleoplasm
Pathways (Reactome):
Developmental Biology: Cardiogenesis; Formation of axial mesoderm; Formation of paraxial mesoderm; Germ layer formation at gastrulation; Regulation of MITF-M-dependent genes involved in cell cycle and proliferation; Regulation of MITF-M-dependent genes involved in pigmentation; Somitogenesis; Transcriptional and post-translational regulation of MITF-M expression and activity; Transcriptional regulation of granulopoiesis
Signal Transduction: Binding of TCF/LEF:CTNNB1 to target gene promoters; Ca2+ pathway; Deactivation of the beta-catenin transactivating complex; Formation of the beta-catenin:TCF transactivating complex; Repression of WNT target genes
Gene expression (Transcription): RUNX3 regulates WNT signaling; Transcriptional Regulation by VENTX
Immune System: Regulation of PD-L1(CD274) transcription
Gene Ontology:
Molecular function: armadillo repeat domain binding; beta-catenin binding; C2H2 zinc finger domain binding; DNA-binding transcription activator activity, RNA polymerase II-specific; DNA-binding transcription factor activity; DNA-binding transcription factor activity, RNA polymerase II-specific; gamma-catenin binding; histone deacetylase binding; nuclear estrogen receptor binding; protein binding; RNA polymerase II cis-regulatory region sequence-specific DNA binding; RNA polymerase II transcription regulatory region sequence-specific DNA binding; sequence-specific DNA binding; sequence-specific double-stranded DNA binding; transcription corepressor binding; transcription regulator inhibitor activity; DNA binding; DNA binding, bending
Biological process: canonical Wnt signaling pathway; cell chemotaxis; cellular response to cytokine stimulus; cellular response to interleukin-4; host-mediated activation of viral transcription; negative regulation of apoptotic process; negative regulation of apoptotic process in bone marrow cell; negative regulation of DNA binding; negative regulation of DNA-templated transcription; negative regulation of interleukin-13 production; negative regulation of interleukin-4 production; negative regulation of interleukin-5 production; negative regulation of transcription by RNA polymerase II; neutrophil differentiation; osteoblast differentiation; positive regulation of cell migration; positive regulation of cell proliferation in bone marrow; positive regulation of DNA-templated transcription; positive regulation of epithelial to mesenchymal transition; positive regulation of gene expression; positive regulation of granulocyte differentiation; positive regulation of transcription by RNA polymerase II; protein localization to chromatin; epithelial to mesenchymal transition; positive regulation of cell differentiation; and 9 more
Cellular component: beta-catenin-TCF complex; cytoplasm; nucleus; protein-DNA complex; transcription regulator complex; chromatin; nucleoplasm
Genetic constraint (gnomAD): Loss-of-function variants: 11 observed, 39.7 expected, observed/expected ratio (o/e) 0.28, 90% interval 0.17 to 0.46. The upper end of that interval is the gene's LOEUF score, 0.46, which puts it in group 2 of 6, group 1 being the genes least tolerant of losing a copy. Missense variants: 323 observed, 450.17 expected, observed/expected ratio (o/e) 0.72, 90% interval 0.65 to 0.79. Synonymous variants: 156 observed, 166.99 expected, observed/expected ratio (o/e) 0.93, 90% interval 0.82 to 1.07.
Cancer hallmarks: invasion and metastasis (promotes); proliferative signalling (promotes)
Homologues: Orthologues: chimpanzee LEF1 (98% identical), macaque LEF1 (98% identical), dog LEF1 (97% identical), mouse Lef1 (97% identical), guinea pig LEF1 (97% identical), rabbit LEF1 (97% identical), rat Lef1 (95% identical), pig LEF1 (94% identical), tropical clawed frog lef1 (80% identical), zebrafish lef1 (77% identical). Paralogues in human: TCF7L2 (63% identical), TCF7L1 (57% identical), TCF7 (46% identical).
Diseases named in the same sentence as LEF1 in open-access papers:
LEF1 is named in the same sentence as 238 diseases in open-access papers, as found by Europe PMC text mining. Sharing a sentence is not in itself a finding about the gene and the disease. The quoted sentences say what the papers report.
breast carcinoma (75 papers, 2010 to 2026). "Meanwhile, LEF1 has been identified as a useful diagnostic marker for the development, metastases, and poor prognoses in several cancers, including chronic lymphocytic leukemia, breast cancer, liver cancer, prostate cancer." (PMID 37657935, 2023). "In addition, it was reported that LEF1 was implicated in cell invasion and metastasis of breast cancer." (PMID 34256750, 2021). "The risk score of breast cancer prognosis was determined with the following formula: RiskScore = 0.629*ANO6 + 0.147*CELSR3 + 0.381*CLDN7+ 0.273*EPB41L4B-0.357*FAM166B -0.843*GPLD1–0.202*LEF1–0.202*PPARG -0.127*SUSD3." (PMID 34364397, 2021). "In breast cancer, Elp3 is associated with tRNA modification and the IRES-dependent translation of LEF1 to maintain metastasis in breast cancer." (PMID 41501031, 2026). "LEF1 regulates breast cancer cell proliferation, and IGF2R enhances tumor cell invasion and migration and serves as a poor prognostic marker in triple-negative breast cancer patients." (PMID 41511940, 2026). "In our study, we observed a significant presence of LEF1‐positive CAFs within the stroma of human breast cancers, particularly in cases of SCC." (PMID 39887653, 2025). "This study has identified LEF1‐expressing CAFs within the breast cancer stroma and proposed their involvement in tumor growth and SCC formation." (PMID 39887653, 2025). "Taken together, these findings suggest that stromal LEF1 expression is correlated with poor prognosis in breast cancer." (PMID 39887653, 2025). "Subsequently, we analyzed tumor specimens from breast cancer patients and found that LEF1‐positive CAFs are abundant and cancerous region‐specific." (PMID 39887653, 2025). "Given the prevalence of LEF1‐positive CAFs in SCC in breast cancer patient specimens, we evaluated xenograft tumors using SCC markers, p40 and CK5/6." (PMID 39887653, 2025). "Since LEF1‐positive CAFs were identified in the tumor stroma of breast cancer patients, we aimed to investigate the significance of LEF1 expression in CAFs using our exp‐CAF system." (PMID 39887653, 2025). "In this study, we observed expression of LEF1 in exp‐CAF 544 cells derived from human mammary fibroblasts coimplanted with human breast cancer cells in a mouse model." (PMID 39887653, 2025). "In breast cancer, inhibition of LEF1 reduces phthalate-activated cell growth, invasion, and migration." (PMID 39744480, 2025). "In summary, our study reveals the abundance of LEF1‐expressing CAFs in breast cancer stroma and proposes that LEF1 expression plays a role in the tumor‐promoting ability of breast CAFs and potentially mediating transdifferentiation toward SCC." (PMID 39887653, 2025). "Next, we examined the proportion of LEF1‐positive fibroblasts using immunohistochemistry in 20 breast cancer patient samples with α‐SMA‐positive tumor stroma." (PMID 39887653, 2025). "Regarding the biomarker potential in breast cancer, our resultssuggest that LEF1, TCF3, TCF4, and specially TCF7, have significant diagnostic valueto distinguish breast cancer patients from healthy individuals and a role insubtyping insight." (PMID 38100720, 2023). "In this study, we used bioinformatic analysis to perform anin-depth investigation of the expression pattern and clinicopathologicalassociations of the LEF1/TCF family members in breast cancer." (PMID 38100720, 2023). "In this study, we evaluated in silico the clinical and functionalrelevance of the LEF1/TCF family members in breast cancer." (PMID 38100720, 2023). "In breast cancer,LEF1 acts in metastatic processes and is one of the few commonlyover-expressed genes in brain-seeking breast cells." (PMID 38100720, 2023). "LEF1 regulates glutathione metabolism, increases chemotherapy resistance, and promotes breast cancer brain metastasis." (PMID 35060926, 2022). "siRNA knocking down LOC641518 down-regulates LEF1 mRNA expression, and reduces the migration and invasion capability of breast cancer cells." (PMID 34256750, 2021).
breast carcinoma (continued). "Treatment with quercetin also decreased lymphoid enhancer-binding factor-1 (Lef1) in docetaxel-resistant breast cancer cells and re-sensitized these cells to docetaxel, acting synergistically to reduce the viability of the drug-resistant cells." (PMID 32708138, 2020). "We apply GVITamIN on a breast cancer cohort and identify well-known cancer-related transcription factors, such as CTCF, LEF1, and FOXA1, as TFs dysregulated by breast cancer-associated SNPs." (PMID 32850701, 2020). "Nonetheless, we recently showed that Lef1 is expressed in a small subpopulation of breast cancer cells in half of tumor samples, providing them with an elevated drug resistance." (PMID 32492961, 2020). "Upregulation of Lef1 in breast cancer parental cells induced an upregulation of a combination of proteins, eventually inducing drug resistance." (PMID 32492961, 2020). "Given the important role of LEF1 in EMT and LSD1 is enriched at the transcriptional start site of the LEF1 gene in breast cancer, we focused our attention on LSD1-regulated LEF1 in BCa." (PMID 32850370, 2020). "The fact that LEF1 was significantly associated with a relatively high number of SNPs, which are not in linkage disequilibrium, nor inducing the same cohort splitting, in our analyses might be additional evidence in support of its pivotal role in breast cancer." (PMID 32850701, 2020). "Transwell experiments showed a dramatic inhibition of cell migration and invasion due to the reduction of β-catenin, TCF4, and LEF1 in the breast cancer cells." (PMID 31824307, 2019). "IL1β treatment significantly increased Wnt signalling in a 293T cell Wnt-reporter model (p < 0.0001), and Lef1 Wnt target gene expression in breast cancer cell lines (MCF7; p < 0.0001, MDA-MB-231_BH; p = 0.0083)." (PMID 31676788, 2019). "Elongator has been reported to regulate the IRES-dependent translation of LEF1 to promote breast cancer metastasis by regulating the codon-specific translation of the ITAF protein DEK34." (PMID 31792210, 2019). "Initially, we used activation of a (transcription factor)/LEF-1-dependent luciferase reporter construct (TOPFLASH) in MCF7 (a luminal breast cancer cell line) to assess the effect of MSI2 overexpression on Wnt signalling." (PMID 29093438, 2017). "Stimulation of Wnt-signaling is predicted to activate the canonical Wnt responsive gene CyclinD1, which promotes breast cancer proliferation as well as LEF1 and TCF4, which are transcriptional mediators of the Wnt pathway." (PMID 27738322, 2016). "Phthalates are important in breast cancer progression; they can induce translocation of β-catenin into the nucleus and activate the response transcription factors LEF-1/TCF to induce downstream target gene expression." (PMID 26750754, 2016). "In our current study, we synthesized a small peptide TAT-NLS-BLBD-6 (ATDEMIPF), which is a Wnt/β-catenin signaling inhibitor and prevents the binding of β-catenin to LEF-1 at the nuclear region of human breast cancer cells." (PMID 26750754, 2016). "This increase in β-catenin expression would be expected to interact with and increase TCF/LEF1 target gene expression in these cells, a pathway contributing to breast cancer progression." (PMID 24534923, 2014). "Well established downstream targets, AXIN2 and LEF1 showed higher expression in breast cancer cell lines suggesting activation of canonical WNT signalling." (PMID 23861811, 2013). "Our results are consistent with existing data which suggest activation of WNT signalling in breast cancer through the increased expression of key signalling components and downstream target such as LEF1 at both the mRNA and protein level." (PMID 23861811, 2013). "LEF1 has shown the most consistent activation in breast cancer cell lines and increased expression in BCSCs in both ER−ve and ER+ve patient breast cancer samples." (PMID 23861811, 2013).
breast carcinoma (continued). "As expected and previously reported for breast cancer-derived tumor cells, LEF1 depletion resulted in decreased steady state SNAI2 protein as well as mRNA levels." (PMID 23677615, 2013). "Our current study shows that BPP induces LEF-1 expression to promote cell growth, invasion and migration in breast cancer." (PMID 22905168, 2012). "Furthermore, tissue microarray analysis indicated that stromal LEF1 staining serves as an independent prognostic factor for poor outcomes in breast cancer." (PMID 39887653, 2025). "Additionally, quercetin resensitizes docetaxel-resistant breast cancer cells by inhibiting the expression of Lef1 and decreasing Smad-dependent TGF-β signaling pathway activation." (PMID 38742934, 2024). "In breast cancer, the LEF1/TCF family members alsohave a distinctive role in tumorigenesis." (PMID 38100720, 2023). "Reduced LEF1 could enhance the sensitivity of breast cancer cells to resensitizing docetaxel, and LEF1 downregulation could also inhibit the growth of osteosarcoma cells." (PMID 35340229, 2022). "Indeed, Lef1 expressing cell amount was negligible, and close to 0 in the luminal A subtype of breast cancer cell parental lines MCF7 and ZR-75 cells." (PMID 32492961, 2020). "LEF1 is an important transcription factor involved in the activation of the Wnt signaling pathway, and facilitates the synthesis of mesenchymal fibronectin and promotes epithelial-mesenchymal transition in breast cancer." (PMID 31897227, 2020). "In addition to these reports, we recently found that the induction of Lef1 expression in the luminal A subtype of breast cancer cells increased their resistance to DTX." (PMID 32492961, 2020). "Moreover, in vitro analysis has shown that quercetin reversed DTX resistance and induced apoptosis by suppressing LEF1 expression in DTX-resistant MCF7 breast cancer cells." (PMID 32933177, 2020). "To determine whether the β-catenin/LEF-1 pathway indeed participates in regulating FUT8 expression in breast cancer cells, we examined the effect of shRNA-mediated β-catenin knockdown on the expression of FUT8 in MDA-MB-231 cells." (PMID 28982386, 2017). "Concordantly, the expression levels of multiple downstream targets of Wnt/β-catenin signaling, namely cyclin D1, c-MYC, TCF4 and LEF1, and nuclear β-catenin, were increased in the miR-1229–overexpressing breast cancer cells but decreased in the miR-1229–silenced breast cancer cells." (PMID 26992223, 2016). "In addition, LEF1 is overexpressed in a subset of canine mammary carcinomas, implicating LEF1 in ligand-independent activation of canonical Wnt signaling in canine mammary tumors." (PMID 24887235, 2014). "Lower levels of Lef1 were also predictive of recurrence in breast cancer within the ER+ve subgroup." (PMID 23861811, 2013). "Therefore, our studies established that LEF-1 plays a critical role in the estrogenic effects of BPP in breast cancer cells." (PMID 22905168, 2012). "Our study reveals that lymphoid enhancer‐binding factor 1 (LEF1), a central transcription factor for Wnt/β‐catenin signaling, is expressed in experimentally generated tumor‐promoting CAFs (exp‐CAFs) as well as in CAFs from breast cancer patients, particularly those with a poor prognosis." (PMID 39887653, 2025). "Namely, LEF1 is part of the Wnt/β-catenin signaling pathway, which includes for example genes such as c-Myc, LBH, Oct4, NANOG that have been associated with the upregulation of proteins typically involved in human breast cancer, gastrointestinal tumors, prostate cancer, leukemia, and others." (PMID 38003292, 2023). "Thus, we attempted to synthesize a peptide (TAT-NLS-BLBD-6) that could interfere with the interaction of β-catenin and LEF-1 at nuclei in human breast cancer cells." (PMID 26750754, 2016). "In summary, we suggest that LEF1, TCF3,TCF4, and TCF7 have the potential to bebiomarkers in breast cancer clinics." (PMID 38100720, 2023).